JUN (Jun proto-oncogene, AP-1 transcription factor subunit)
Description:
Transcription factor that recognizes and binds to the AP-1 consensus motif 5'-TGA[GC]TCA-3'. Heterodimerizes with proteins of the FOS family to form an AP-1 transcription complex, thereby enhancing its DNA binding activity to the AP-1 consensus sequence 5'-TGA[GC]TCA-3' and enhancing its transcriptional activity (By similarity). Together with FOSB, plays a role in activation-induced cell death of T cells by binding to the AP-1 promoter site of FASLG/CD95L, and inducing its transcription in response to activation of the TCR/CD3 signaling pathway. Promotes activity of NR5A1 when phosphorylated by HIPK3 leading to increased steroidogenic gene expression upon cAMP signaling pathway stimulation. Involved in activated KRAS-mediated transcriptional activation of USP28 in colorectal cancer (CRC) cells. Binds to the USP28 promoter in colorectal cancer (CRC) cells. (Microbial infection) Upon Epstein-Barr virus (EBV) infection, binds to viral BZLF1 Z promoter and activates viral BZLF1 expression.
Synonyms: AP1; c-Jun; AP-1; cJUN; p39
Tractability: Small molecule: a structure with a bound ligand is known; a high-quality ligand is known; it belongs to a druggable protein family. PROTAC: UniProt records ubiquitination sites on it; ubiquitination databases record sites on it; a small molecule that binds it is known.
Target class: Transcription factor
Gene: Protein-coding gene on chromosome 1 (58,776,845 to 58,784,048, reverse strand). Ensembl gene ENSG00000177606.
Subcellular location: Nucleus
Subcellular location (Human Protein Atlas): Nucleoplasm
Pathways (Reactome):
Signal Transduction: Estrogen-dependent gene expression; MAPK6/MAPK4 signaling; Pre-NOTCH Transcription and Translation; Regulation of PTEN gene transcription
Disease: Deregulated CDK5 triggers multiple neurodegenerative pathways in Alzheimer's disease models; Signaling by ALK fusions and activated point mutants; WNT5:FZD7-mediated leishmania damping
Immune System: Activation of the AP-1 family of transcription factors; FCERI mediated MAPK activation; Regulation of PD-L1(CD274) transcription
Cellular responses to stimuli: Oxidative Stress Induced Senescence; Senescence-Associated Secretory Phenotype (SASP)
Developmental Biology: Activation of anterior HOX genes in hindbrain development during early embryogenesis; Differentiation of naive CD4+ T cells to T helper 2 cells (Th2 cells)
Gene Ontology:
Molecular function: cAMP response element binding; DNA-binding transcription activator activity, RNA polymerase II-specific; DNA-binding transcription factor activity; DNA-binding transcription factor activity, RNA polymerase II-specific; DNA-binding transcription repressor activity, RNA polymerase II-specific; enzyme binding; general transcription initiation factor binding; GTPase activator activity; identical protein binding; protein binding; R-SMAD binding; RNA binding; RNA polymerase II cis-regulatory region sequence-specific DNA binding; RNA polymerase II-specific DNA-binding transcription factor binding; sequence-specific double-stranded DNA binding; transcription cis-regulatory region binding; ubiquitin protein ligase binding; ubiquitin-like protein ligase binding; DNA binding; chromatin binding; double-stranded DNA binding
Biological process: host-mediated activation of viral transcription; host-mediated suppression of viral transcription; negative regulation of DNA binding; negative regulation of DNA-templated transcription; negative regulation of transcription by RNA polymerase II; positive regulation of DNA-templated transcription; positive regulation of DNA-templated transcription initiation; positive regulation of miRNA transcription; positive regulation of transcription by RNA polymerase II; positive regulation of vascular associated smooth muscle cell proliferation; regulation of transcription by RNA polymerase II; release from viral latency; response to endoplasmic reticulum stress; SMAD protein signal transduction; transforming growth factor beta receptor signaling pathway; transforming growth factor beta1 production; integrated stress response signaling; JNK cascade; regulation of cell cycle; regulation of cell population proliferation; response to steroid hormone; cellular response to anisomycin; regulation of DNA-templated transcription
Cellular component: chromatin; euchromatin; nucleoplasm; nucleus; RNA polymerase II transcription regulator complex; transcription factor AP-1 complex; nuclear chromosome; transcription regulator complex; transcription repressor complex
Genetic constraint (gnomAD): Loss-of-function variants: 7 observed, 18.36 expected, observed/expected ratio (o/e) 0.38, 90% interval 0.22 to 0.72. The upper end of that interval is the gene's LOEUF score, 0.72, which puts it in group 2 of 6, group 1 being the genes least tolerant of losing a copy. Missense variants: 373 observed, 447.46 expected, observed/expected ratio (o/e) 0.83, 90% interval 0.76 to 0.91. Synonymous variants: 246 observed, 207.77 expected, observed/expected ratio (o/e) 1.18, 90% interval 1.07 to 1.32.
Homologues: Orthologues: macaque JUN (99% identical), pig JUN (98% identical), mouse Jun (97% identical), rat Jun (97% identical), dog JUN (96% identical), rabbit JUN (94% identical), tropical clawed frog jun (73% identical), zebrafish jun (73% identical), guinea pig JUN (56% identical), Drosophila melanogaster Jra (33% identical), Caenorhabditis elegans F19B2.6 (28% identical). Paralogues in human: JUND (51% identical), JUNB (49% identical).
Diseases named in the same sentence as JUN in open-access papers:
JUN is named in the same sentence as 486 diseases in open-access papers, as found by Europe PMC text mining. Sharing a sentence is not in itself a finding about the gene and the disease. The quoted sentences say what the papers report.
breast cancer (241 papers, 2005 to 2025). A primary or metastatic malignant neoplasm involving the breast. "Our results disclosed that higher expression of PTGS2/ESR2/EGFR/JUN/MMP2 genes’ signature associated with the most aggressive breast cancer subtypes donating by basal breast cancer (P < .00001) and the ER-negative breast tumors ( P < .00001)." (PMID 39707884, 2024). "In this study, as well as in certain bioinformatic analyses related to dementia, JUN (also known as c-JUN), a proto-oncogene primarily associated with breast cancer, has been identified." (PMID 39766348, 2024). "EN is known to activate ERK and AKT signaling, and AP-1 (JUN/FOS) activation is implicated in breast cancer initiation; also, the EN relies on functional IGF1R signaling in the host cell." (PMID 37686522, 2023). "To further test the roles of stromal JUN activation in tumor progression, we tried to examine how fibroblast-specific loss of JUN affects breast cancer progression." (PMID 36438487, 2022). "In patients with short survival time (< 5 years), the expression of JUN in breast cancer tissue is down-regulated and the risk of recurrence of breast cancer is increased." (PMID 35127514, 2021). "In summary, breast cancer stroma-related genes, including JUN, FOS, ATF3, STAT1, COL1A1 and FN1, were all associated with tumor invasion and metastasis." (PMID 30237810, 2018). "Moreover, JUN has association with a variety of tumors, such as breast cancer and non–small cell lung cancer, and c-Jun is upregulated and activated in CC cells through its transcriptional activity." (PMID 36880057, 2023). "In KEGG analysis, GLUT1 and JUN are associated with seven breast cancer related pathways." (PMID 36476606, 2022). "Candidate pathways were constructed starting from the estrogen receptor ESR1 gene and targeting breast cancer-associated transcription factors, such as JUN, FOS, STAT1, STAT3, STAT5A, ELK1, and ETS1 (Target transcription factors were pre-identified by GibbsOS19)." (PMID 33432018, 2021). "When we assessed the proliferation of cancer cells through the expression of the Ki67 marker, exposure to GA (10 μM) provoked a decrease in proliferation and it reduced the levels of JUN, a transcription factor associated with the proliferation of breast cancer cells." (PMID 31578236, 2019). "The present study is the first to use bioinformatics and laboratory experiments to demonstrate that the increased mRNA expression of GLUT1 was also associated with poor prognosis and metastasis in breast cancer, which may be regulated via JUN by binding to GLUT1 promoter." (PMID 36476606, 2022). "JUN, a downstream effector of JNK, has also been implicated as an oncogene in ER+ breast cancer, reinforcing the complexity of JNK’s role in modulating ER signalling and therapy insensitivity." (PMID 40826108, 2025). "In order to study the relationship between ABCB1 (MDR1) and JUN expressions in breast cancer clinical samples, we analyzed TCGA transcriptomic databases." (PMID 39470848, 2025). "Breast cancer patients with elevated expression of PTGS2/ESR2/EGFR/JUN/MMP2 genes’ signature displayed significantly poor OS (P = 0.026) and DMFS (P = 0.0066) and consequently unfavorable prognosis." (PMID 39707884, 2024). "The biological function of CCDC88C in breast cancer metastasis was at least partially mediated by c-JUN-induced CEMIP transcription." (PMID 38971758, 2024). "CEMIP, located on chromosome 15q25, serves as a downstream gene of c-JUN, and its transcription is reduced by knockdown of c-JUN in breast cancer cells." (PMID 38971758, 2024). "We identified changes in transcriptional levels of CEMIP in breast cancer cells induced by CCDC88C that required c-JUN." (PMID 38971758, 2024). "A microarray dataset GSE195842 identified the DEGs in breast cancer cells between the si-JUN and si-nc groups." (PMID 38971758, 2024). "c-JUN is a potential regulator that stimulates the transformation of breast cells into HR+/HER2-type breast cancers." (PMID 39376611, 2024).
breast cancer (continued). "It is vital to identify the likely biological processes and cellular functions by which PTGS2/ESR2/EGFR/JUN/MMP2 genes’ signature exhibited their tumorigenic effect in breast cancer." (PMID 39707884, 2024). "It was reported that in breast cancer AP-1 transcription factor components, i.e., JUN, JUNB, FOS, FOSB, in addition to DUSP1, EGR1, NR4A1, IER2 and BTG2, behave as a conserved co-regulated network 14, most of which are transcriptional factors." (PMID 37057290, 2023). "By qRT-PCR, we verified that GLUT1 was significantly increased in 38 paired human breast cancer samples while JUN was decreased." (PMID 36476606, 2022). "The mRNA expression (p < 1E− 12) and protein phosphorylation level at T239S243 (P = 0.002) of JUN significantly decreased in breast cancer (UALCAN database)." (PMID 36476606, 2022). "As shown by IHC analysis in tissue microarrays, p-JUN levels are significantly higher in breast cancer stroma, compared to corresponding para-cancerous tissues." (PMID 36438487, 2022). "In our report, the mRNA expression and protein phosphorylation at T239S243 of JUN were significantly downregulated in breast cancer tissues." (PMID 36476606, 2022). "To explore underlying pathways, we further performed GO and KEGG analysis of genes related to GLUT1 and JUN and found that GLUT1 was increased by transcription factor c-Jun in breast cancer tissues to influence glycolysis and breast cancer metastasis." (PMID 36476606, 2022). "More importantly, we demonstrate that the inhibition of JUN transcriptional activity disrupts the AP-1 regulatory networks in CAFs and attenuates breast cancer metastasis in vitro and in vivo." (PMID 36438487, 2022). "In line with this, we find that JUN protein is highly activated in the stroma of metastatic breast cancers." (PMID 36438487, 2022). "In this review, we examine the role of crosstalk between PRLR and ERBB1/2 signaling pathways in the activation of unliganded ERα, cyclin-D1 and other oncogenic factors (MYC, FOS, JUN) in breast cancer." (PMID 34572912, 2021). "Strikingly, phosphorylation of the transcription factor c-JUN, described as a central molecular mediator in fibrotic conditions and hyperactivated in high density stroma breast cancer tissue, was higher in high-NRG1 CAFs (CAF#2, CAF#3, CAF#6)." (PMID 33692466, 2021). "The second highest transcriptional regulator in GE2-HCC was the proto-oncogene JUN, overexpression of which has been shown to reprogramme oestrogen receptor signalling in breast cancer cells and confer them resistance to tamoxifen." (PMID 33541355, 2021). "JUN overexpression induced oncogenic transformation, increased tumor formation, and invasion in human breast cancer cells." (PMID 34437475, 2021). "Especially, ectopically expressed JUN augments invasiveness of less invasive breast cancer cells while suppressing JUN expression inhibits invasion and metastasis." (PMID 34244488, 2021). "With regard to brain metastasis in breast cancer, a recent study demonstrated that phosholylation of EZH2, which is highly expressed in brain metastatic breast cancer cells, causes c-JUN upregulation and increased G-CSF secretion." (PMID 34405029, 2021). "Transfection of cells with vectors encoding COP1 and constitutively activated GSK-3β resulted in decreased levels of c-JUN expression and the invasive breast cancer cells." (PMID 32365809, 2020). "To test this possibility, we further examined the correlation between the expressions of EMT genes, Bcl-2, and JNK target gene JUN in both patient tumors and CTCs and the survival of breast cancer patients." (PMID 33143160, 2020). "The constitutive photomorphogenesis protein 1 (COP1) is an E3 ligase which was determined to be responsible for c-JUN degradation in less-invasive breast cancer cells." (PMID 32365809, 2020). "GSK-3 inhibitors (lithium chloride and SB21673) increased c-JUN protein levels in less-invasive breast cancer cells." (PMID 32365809, 2020).
breast cancer (continued). "Together, our findings from clinical samples demonstrated a positive association between the expression of JUN and lung metastasis in patients with breast cancer, and suggested that c-Jun play an important role in BCLM." (PMID 29667003, 2019). "In conclusion, JUN, FOS, ATF3 and STAT1 have been reported to be associated with breast cancer invasion and directly or indirectly participate in ECM remodeling." (PMID 30237810, 2018). "MED1 mediates induction of cell proliferation and migration and the genes associated with it (JUN, FOS, EGFR, VEGF, MMP1, and ERBB4) in breast cancer, which is abrogated when used together with miR-191-inhibition." (PMID 30087366, 2018). "The activation of JUN was also involved in the progress of breast cancer, gastric cancer, and colorectal carcinomas." (PMID 28673327, 2017). "Several nodes in this pathway emerged as potential direct targets of EGCG in breast cancer: JUN, FADD, NFKB1, Bcl-2, GNAO1, and MMP14." (PMID 28713815, 2017). "DOCK1 gene expression carries prognostic significance in breast cancer, ovarian cancer and glioblastoma multiforme through activation of c-JUN, STAT3, and Rac1." (PMID 29069784, 2017). "The results suggest that signaling proteins affected by EGCG in breast cancer, which include JUN, FADD, NFKB1, Bcl-2, GNAO1, and MMP14, are involved primarily in cell death and survival; DNA replication, recombination and repair; and the cell cycle." (PMID 28713815, 2017). "For example, in breast cancer, studies have found that the activation of the JUN TF binding to specific enhancers in CAFs drives the reprogramming of these enhancers, thus activating the expression of a series of genes that promote tumor invasiveness and metastasis." (PMID 40032852, 2025). "Bioinformatics analysis also showed that JUN may bind to the GLUT1 promoter in breast cancer tissues, downregulating its gene expression or mRNA stability, thereby inhibiting glycolysis." (PMID 40332792, 2025). "Therefore, MAP2K7 is a probable primary driver of JUN stability via the JNK pathway in ER+ breast cancer." (PMID 40826108, 2025). "Finally, we examined the relationship between JNK pathway genes and JUN/JUND expression in primary ER+ breast cancers from the TCGA (n = 812)." (PMID 40826108, 2025). "In addition, a bioinformatics analysis of TCGA breast cancer BRCA database showed a strong positive correlation between JUN and ABCB1, confirming our results that c-Jun potentiates the MDR1 expression in BC cells." (PMID 39470848, 2025). "The hyperactivation of the JUN oncogene has made it a critical therapeutic target in breast cancer." (PMID 40259961, 2024). "Moreover, recent analyses of ZEB1 genomic binding sites in breast cancer show that ZEB1 binding sites extensively overlap with both AP-1 (33% ZEB1 overlap with c-JUN) and YAP binding sites." (PMID 37176013, 2023). "JUN is an inflammation-related gene and participates in the development of different human cancers such as breast cancer, non-small cell lung cancer, colorectal cancer, and recent studies revealed that JUN was also significantly correlated to overall survival of cancer patients." (PMID 37745978, 2023). "Moreover, the activation of c-JUN and AVPR1A target genes were associated with the invasive expressions of breast cancer cells, including enhanced tumor proliferation and angiogenesis." (PMID 37737712, 2023). "While an increase of KDM3A is concomitant with a reduced H3K9me2/3 during breast tumorigenesis, KDM3A facilitated the activation of genes implicated in breast cancer as MYC, PAX3, Cyclin D1, MMP-9, S100A4, and JUN, thereby enhancing the proliferation and motility of breast cancer cells." (PMID 36185256, 2022). "Furthermore, GLUT1 was upregulated in 38 paired human breast cancer tissues while JUN was downregulated by qRT-PCR." (PMID 36476606, 2022). "Furthermore, JUN mediates the functions of some important cytokines in breast cancer, such as IL-34, IL-33, and IL-1β." (PMID 35127514, 2021).